INS (insulin)
Diseases named in the same sentence as INS in open-access papers (continued):
Sharing a sentence is not in itself a finding about the gene and the disease.
diabetes (continued). "Type 2 diabetes mellitus (T2DM) is characterized as a disorder of impaired energy metabolism caused by insufficient insulin production and/or decreased insulin sensitivity." (PMID 35052401, 2021). "Previous studies on CGM accuracy compared to blood glucose concentrations have included people with diabetes during a liquid meal test, insulin-induced hypoglycaemic conditions, or during a 24-hour hospital stay (not OGTT)." (PMID 34675886, 2021). "With respect to diabetes development, numerous studies suggest that the saturated fat palmitic acid is particularly detrimental to beta-cell function and promotes insulin resistance." (PMID 34234216, 2021). "As IR and autoimmunity are often part of the clinical course of diabetes, clinical trials are needed to explore the benefit of diet/healthy lifestyle, insulin-sensitizing agents, and immunomodulating therapies on distinct diabetes endotypes." (PMID 34902055, 2021). "For example, there are 20,467 cases (without missing values) in 2007Q1, and 3877 (18.94%) of them contain “Diabetes Mellitus Non-Insulin-Dependent”." (PMID 34709197, 2021). "The use of insulin to treat patients with diabetes led Harold Himsworth to observe that there are two types of patients, the insulin-sensitive and insulin-resistant ones." (PMID 34440929, 2021). "Type 2 diabetes mellitus (T2DM) is characterized by chronic hyperglycemia and relative deficiency of insulin, resulting in disorders of lipid, glucose and protein metabolisms." (PMID 33981226, 2021). "Statistically significant differences were found among the groups regarding the distribution of age (P = 0.005), SOFA score (P < 0.001), diabetes (P < 0.001), renal failure (P < 0.001), and use of insulin (P < 0.001)." (PMID 33833344, 2021). "Variables observed included the use of HBOT and normobaric conditions in people with diabetes mellitus (mainly those with type 2 diabetics mellitus) with assessment of changes in insulin levels, insulin sensitivity, OGTT, and HbA1c." (PMID 34684171, 2021). "On the other hand, the most common form is Type 2 DM (T2DM), once referred to as adult-onset diabetes or non-insulin-dependent diabetes mellitus, which occurs when the body becomes resistant to insulin, namely when cells fail to respond to insulin properly." (PMID 34501572, 2021). "Surprisingly, 34% of the institutions that administered CCDs to patients who take insulin to manage their diabetes used a simple CHO beverage." (PMID 34044894, 2021). "Twenty-one days after alloxan-induced diabetes, mice presented increased blood glucose levels with a simultaneous reduction of body weight and plasma insulin levels, indicating a diabetic state." (PMID 34295325, 2021). "Another study originally revealed the possible regulatory effects of Fam20C on (pro)insulin production and correlative secretory pathway trafficking, establishing connections between Fam20C function and the development of diabetes." (PMID 34988120, 2021). "We aimed to determine the effect of short-term intensive insulin therapy (SIIT) on long-term glycemic control in newly-diagnosed Type-2 diabetes mellitus (nT2DM) patients." (PMID 34912428, 2021). "Type 1 diabetes (T1D), previously known as juvenile diabetes, is characterized by impaired insulin secretion; it represents 5–10% of all diabetes cases and needs to be treated with insulin." (PMID 34681954, 2021). "To celebrate this centenary, we explore areas of ongoing insulin research in diabetes, metabolic syndrome and beyond." (PMID 34752619, 2021). "Until recently, there were no direct electronic means of communication between the glucose monitoring and insulin delivery systems, such that a young person with diabetes or a parent/caregiver would need to make all decisions." (PMID 33528374, 2021). "The use of pluripotent stem cells as an unlimited cell source to generate insulin‐producing cells for implant is a promising alternative for treating diabetes." (PMID 34387389, 2021).
diabetes (continued). "Treatment of diabetes consisted strictly of dietary interventions for 19.5% of patients, whereas 67.5% took oral blood glucose lowering drugs and 13.0% used insulin therapy." (PMID 33627317, 2021). "Pancreatic beta cells secrete insulin in response to stimulation with glucose and other nutrients, and impaired insulin secretion plays a central role in development of diabetes mellitus." (PMID 34359828, 2021). "Our study showed that most of the MIDD patients (79/102,77.45%) received insulin therapy, 37.18% (29/78) initiated insulin once diabetes was diagnosed, and less than one-fourth (24/102,23.53%) did not use insulin." (PMID 34899594, 2021). "Recent studies documented the link between high body mass index (BMI) and diabetes via proinflammatory cytokines, insulin resistance, increased levels of circulating fatty acids, and impaired cellular metabolism." (PMID 34442032, 2021). "Since fasting plasma insulin was similar in diabetics than in control animals, the high blood glucose was due to insulin resistance and the inability of the pancreas to compensate by increasing insulin production." (PMID 34202017, 2021). "Metformin is the first-line type 2 diabetes mellitus treatment that works by reducing insulin resistance and fasting plasma insulin levels, leading to a reduction in blood glucose concentrations without causing overt hypoglycemia." (PMID 34680546, 2021). "In the present meta-analysis, the efficacy and safety of currently available long-acting insulin (insulin degludec and glargine) were compared in type 2 diabetes mellitus Asian patients." (PMID 34345540, 2021). "Medicinal plants used to treat diabetes have high concentrations of K, Ca, Cr, Mn, Cu, and Zn that stimulate the action of insulin and also Fe, Zn, and Cr that act in the prevention of complications of type 2 diabetes." (PMID 33869633, 2021). "GPR81 agonists suppressed fasting plasma FFA levels in rodents and improved insulin sensitivity in mouse models of insulin resistance and diabetes." (PMID 34943862, 2021). "Another study also showed that diabetes status and insulin levels are related to elevated blood pressure." (PMID 34513942, 2021). "The results showed that there was a significant survival difference among non-diabetes group, metformin group and insulin group, 5-year DFS was 85.8%, 96.1%, 73.0%, and 5-year OS was 87.3%, 97.1%, 73.3% respectively (P < 0.05)." (PMID 33976288, 2021). "A well-known SIRT1 activator—resveratrol (RES)—was shown to attenuate diabetes while SIRT1 knockdown leads to insulin resistance, enhanced cholesterol and free fatty acid levels." (PMID 34034759, 2021). "There are several predictors of T2DM remission after bariatric surgery, such as age, diabetes duration, insulin use, glycated hemoglobin (HbA1c), and C-peptide plasma level." (PMID 34378729, 2021). "This shows that the IPC cluster derived from human MSC differentiation replaced impaired islet cells to release insulin in mice, fully proving that IPCs derived from human MSCs can treat diabetes." (PMID 34135959, 2021). "Nevertheless, the management of patients with diabetes is still challenging due to the great economic burden and the need for an acceptable level of education to self-manage insulin therapy." (PMID 34770132, 2021). "Multiple studies have shown altered β-cell autophagy in mouse obesity or diabetes models and the ablation of autophagy in β-cells leads to decreased insulin secretion and impaired glucose tolerance." (PMID 34829881, 2021). "This is likely appropriate, as the clinical consequences of missed insulin doses can be immediately harmful, whereas complications from missed non-insulin diabetes medications are delayed." (PMID 34209616, 2021). "Type 2 diabetes mellitus is a heterogeneous disorder characterized by insulin resistance with varying degrees of insulin secretory defects, followed by reduced insulin secretion from the pancreas (pancreatic beta-cell dysfunction)." (PMID 34299261, 2021).
diabetes (continued). "Studies in rat models have shown that severe maternal diabetes leads to acute fetal hyperglycemia and consequent beta cell hyperplasia, as well as increased insulin output and inability to undergo adaptive beta-cell expansion in adult life." (PMID 34025578, 2021). "As exposure to HFD results in insulin resistance and diabetes, we investigated the effect of chronic treatment with both NAEs on circulating insulin concentrations and insulin resistance." (PMID 34444748, 2021). "Despite novel insulin formulations, patients with diabetes continue to suffer morbidity and mortality with unsustainable costs to the health care system." (PMID 33573247, 2021). "Although PA levels are inversely correlated with BMI, the present results are not simply due to differences in FM, but rather result from lower insulin sensitivity in the diabetes groups." (PMID 34659107, 2021). "As a system for insulin resistance and diabetes drug development, insulin-resistant rodent models have been clearly established, but there is a limitation to high-throughput drug screening." (PMID 34358068, 2021). "Insulin loaded NPs are reported to be prepared by alginate ionotropic pre-gelation followed by polyelectrolyte complexation with chitosan for use in diabetes." (PMID 33430478, 2021). "As diabetes progresses, beta-cell function gradually deteriorates, frequently requiring exogenous insulin supplementation to maintain glycemic target." (PMID 34879878, 2021). "In a recent study from our group, we found that brain insulin resistance measures from persons matched on diabetes status, were related to AD pathology and lower cognitive function." (PMID 33858515, 2021). "In individuals with diabetes mellitus, the levels of insulin increase soon after the onset of the hyperglycemic condition." (PMID 33602249, 2021). "During COVID-19 infection, pancreatic beta cells are forced to secrete an increased amount of insulin due to infection, which is already difficult in people with diabetes." (PMID 33801468, 2021). "Many studies have been based on molecular research to investigate the mechanism of the pancreas to reduce insulin secretion while the blood sugar level of patients with diabetes were higher than the normal range." (PMID 34714885, 2021). "New technology, however, has brought new means of communication between glucose sensing devices, people with diabetes, and insulin delivery systems." (PMID 33528374, 2021). "Currently, conventional therapeutic regimens for diabetes which beyond diet and exercise include daily oral hypoglycemic agents and insulin injections are used to control high blood glucose." (PMID 33705413, 2021). "The centenary of insulin offers a policy window for this to happen and shape the future of access to insulin and diabetes care globally." (PMID 33483763, 2021). "Diabetes mellitus is a prevalent metabolic disorder characterized by hyperglycemia, which results in insulin resistance and insufficient insulin secretion due to the failure of β-pancreatic cells." (PMID 34814918, 2021). "While the influence of bowel dysfunctions is obvious, diabetes is more likely to affect QoL through secondary diseases such as polyneuropathy, or the need for medication such as insulin injections." (PMID 34239041, 2021). "Hepatic cells are sensitive to circulatory TNFα and can impair the canonical insulin signaling pathway, inhibiting glucose uptake and leading to the development of insulin resistance, which precedes type 2 diabetes mellitus." (PMID 34576943, 2021). "Lower incidence of diabetes complications and lower severity of diabetes as well as reduced patient-borne costs have been reported for patients with high adherence to insulin therapy." (PMID 33402226, 2021). "On another note, food microbiome has been a topic of interest regarding diabetes and obesity as it has been shown that food microbiome interactions can improve insulin sensitivity and inflammation response." (PMID 33535684, 2021).
diabetes (continued). "Our results highlight the role of GIGYF1 in regulating insulin signaling and protecting from diabetes." (PMID 34732801, 2021). "miRNAs not only regulate insulin secretion, islet development, islet β-cell differentiation, glucose metabolism, and lipid metabolism, but also contribute to the occurrence of diabetes and its complications." (PMID 34394002, 2021). "Diabetes is characterized by high blood sugar levels that occur as a result of decreased pancreatic insulin production or decreased insulin sensitivity in tissues that typically respond to insulin signaling." (PMID 35011044, 2021). "An initial evaluation of the use of the Cambridge algorithm in toddlers demonstrated the feasibility of hybrid closed-loop insulin delivery in young children with diabetes, whereby parents reported reduced diabetes management burden and improved sleep quality." (PMID 34456876, 2021). "Diabetes patients often suffer, due to insufficient compliance, from later complications despite insulin treatment." (PMID 34834962, 2021). "Diabetes is a set of metabolic diseases recognized by high blood glucose levels arising from complications in insulin production, insulin use, or both." (PMID 33747450, 2021). "An insufficient amount of beta cells or defects in the molecular mechanisms leading to glucose-induced insulin secretion trigger the development of diabetes, a severe disease with epidemic spreading throughout the world." (PMID 33967961, 2021). "According to the report from Japan Diabetes Society, 1 in every 7 Japanese is suffering from diabetes and 95% of them are type 2 diabetes (T2D), which is characterized as impaired insulin secretion and insulin resistance." (PMID 34578896, 2021). "First, diabetes is an endocrine disease involving disorders of the levels of a variety of hormones, including insulin, glucocorticoids, and adrenal hormones." (PMID 33588950, 2021). "One meta-analysis reported that the use of insulin, one of the medications used to treat diabetes mellitus, is related to the development of DR." (PMID 34283877, 2021). "Older adults with worse diabetes severity (i.e., on insulin) manifest significantly decreased VS integration compared to participants with less severe diabetes (diet and/or use of oral hypoglycemic agents), and this was associated with poorer motor outcomes." (PMID 33668979, 2021). "We identified 8744 patients with diabetes mellitus treated with insulin in a primary care or endocrinology clinic affiliated with one of the study institutions." (PMID 33402226, 2021). "Although T1D is commonly managed via exogenous insulin administration, some patients are unable to maintain appropriate glycemic control and require islet engraftment to avoid long-term diabetes-related complications." (PMID 34205321, 2021). "This year marks the 100th anniversary of the pioneering experiments by Banting, and later on Best, Macleod and Collip, that led to the discovery of insulin to treat diabetes." (PMID 35126141, 2021). "Diabetes induced murine models supplemented with insulin showed an increase in testosterone bioavailability, and spermatogonial differentiation of primary spermatocytes." (PMID 33804600, 2021). "Several diabetes-related phenotypes, including hypertriglyceridemia, hypercholesterolemia, impaired glucose tolerance, insulin resistance, impaired insulin secretion, and hyperglycemia, were apparently observed in TSOD mice." (PMID 33435282, 2021). "White fat cells which are dense store energy in patients with diabetes and obesity, while brown fat cells break down for energy and are more sensitive to insulin." (PMID 35284785, 2021). "After diabetes was confirmed, animals were orally treated with the extract, metformin, and insulin according to the experimental design." (PMID 34745283, 2021). "In another study, mice fed with a high-fat diet were used as an animal model of type 2 diabetes mellitus in which insulin resistance was the main metabolic disturbance." (PMID 34589130, 2021).
diabetes (continued). "Diabetes is a serious long-lasting pathological state characterized by an inability of a body to carry out the physiological role of insulin." (PMID 33974529, 2021). "Once the ability for compensated insulin secretion is reached, there is progression to overt diabetes." (PMID 35069433, 2021). "There is a strong evidence base showing the benefits of real-time CGM in people with diabetes receiving insulin, including the DIAMOND T1D/T2D and GOLD T1D studies." (PMID 34184589, 2021). "Due to this, cancer cells can respond to insulin, especially in the conditions of obesity and diabetes where it is greatly expressed." (PMID 34535145, 2021). "In patients with D2M diabetes, irisin showed to play a significant role in insulin sensitivity and metabolic disorders." (PMID 34917685, 2021). "The WHO or other organisations within the United Nations can also develop a pooled procurement mechanism for insulin and diabetes management-related supplies." (PMID 33483763, 2021). "This study concerns glulisine, a rapid-acting insulin analogue that plays a fundamental role in diabetes management." (PMID 33462295, 2021). "This was the first study to demonstrate the feasibility and safety of rtCGM in insulin-treated diabetes." (PMID 33534631, 2021). "Since MG is known to impair insulin signaling and induce insulin resistance, prolonged insulin stimulation, such as diabetes-induced hyperinsulinemia, would result in the overproduction of MG." (PMID 33671767, 2021). "The pancreas maintains the plasma glucose balance by different exocrine hormones, such as insulin and glucagon, and diabetes is a disability of pancreas function." (PMID 34690937, 2021). "A Low Carbohydrate Diet should be offered to all patients with diabetes, especially those using insulin." (PMID 34458301, 2021). "There are a number of factors involved in the regulation of the gene, but glucose, insulin and cytokines are of particular interest in relation to diabetes." (PMID 33477763, 2021). "Diabetes mellitus characterized by hyperglycemia resulting from reducing insulin secretion, insulin action, or both is an endocrine disease that is a global health problem." (PMID 34136578, 2021). "In mouse models of diabetes, PPARβ/δ increases insulin sensitivity through increased glucose catabolism, shunting glucose into lipogenesis pathways and increasing fatty acid oxidation in skeletal muscle." (PMID 33828528, 2021). "Previous studies demonstrated that MG promotes the generation of MDA, which is a product of lipid peroxidation and a marker of dysfunctional insulin expression and diabetes." (PMID 34371651, 2021). "In T1DM, an autoimmune disease corresponding to ~5–10% of all diabetes cases, the immune system destroys the insulin-producing β-cells of the pancreas." (PMID 34574099, 2021). "Diabetes represents a group of metabolic diseases characterized by hyperglycemia resulting from defects in insulin secretion, insulin action, or both." (PMID 34205677, 2021). "FBG and insulin level in the MGO group were significantly higher than in the control group (p < 0.001), which is the strongest index for diabetes induction; Gal and met administration were associated with significantly lower FBG and insulin level (p < 0.001)." (PMID 34568732, 2021). "Remarkably, subcutaneously injection of FGF1 protein can significantly improve the insulin sensitivity and reduce the serum glucose levels in two mouse models of diabetes (ob/ob, db/db and diet-induced obese insulin resistant mice)." (PMID 35011683, 2021). "Diabetes mellitus is a metabolic disorder characterized by hyperglycemia due to defective insulin secretion, action or both." (PMID 35096939, 2021). "These complex mechanisms are focused in diabetes as shown by the remarkable contribution that the Akt protein family can make in suppressing IR and increasing insulin sensitivity." (PMID 34906241, 2021).